OR7A10 (olfactory receptor family 7 subfamily A member 10)
Description:
Odorant receptor.
Synonyms: BC85395_3; OR19-18
Tractability: Antibody: UniProt places it where antibodies can reach, with medium confidence; UniProt predicts a signal peptide or a membrane-spanning region; its Gene Ontology location is reachable by antibodies, with medium confidence.
Gene: Protein-coding gene on chromosome 19 (14,840,466 to 14,848,922, reverse strand). Ensembl gene ENSG00000127515.
Subcellular location: Cell membrane
Pathways (Reactome):
Sensory Perception: Expression and translocation of olfactory receptors
Gene Ontology:
Molecular function: olfactory receptor activity; G protein-coupled receptor activity
Biological process: signal transduction; detection of chemical stimulus involved in sensory perception of smell; G protein-coupled receptor signaling pathway
Cellular component: plasma membrane; membrane
Genetic constraint (gnomAD): Loss-of-function variants: 0 observed, 0.44 expected, observed/expected ratio (o/e) 0, 90% interval 0 to 1.84. That is too few expected variants to judge how well the gene tolerates losing a copy. Missense variants: 358 observed, 386.5 expected, observed/expected ratio (o/e) 0.93, 90% interval 0.85 to 1.01. Synonymous variants: 144 observed, 148.69 expected, observed/expected ratio (o/e) 0.97, 90% interval 0.85 to 1.11.
Homologues: Orthologues: chimpanzee OR7A10 (97% identical), macaque OR7A10 (92% identical), dog OR7A26 (78% identical), dog OR7A52 (78% identical), dog OR7A54 (77% identical), dog OR7A23 (77% identical), dog OR7A53 (76% identical), dog OR7A74 (76% identical), dog OR7A58 (75% identical), mouse Or7a36 (75% identical), mouse Or7a40 (75% identical), dog OR7A69 (74% identical), and 6 more. Paralogues in human: OR7A17 (83% identical), OR7A5 (80% identical), OR7C1 (68% identical), OR7D4 (68% identical), OR7C2 (67% identical), OR7G3 (65% identical), OR7D2 (64% identical), OR7G2 (63% identical), OR7E24 (62% identical), OR7G1 (61% identical), OR1G1 (58% identical), OR1F1 (54% identical), and 116 more.